GSDMD (gasdermin D)
Diseases named in the same sentence as GSDMD in open-access papers (continued):
Sharing a sentence is not in itself a finding about the gene and the disease.
Proptosis (1 paper, 2021). An eye that is protruding anterior to the plane of the face to a greater extent than is typical. "For example, GSDMD expression was elevated in diabetic kidney disease, while suppressing the TLR4/NF-κB pathway induced GSDMD-related proptosis in DKD." (PMID 34692851, 2021).
psoriasis vulgaris (1 paper, 2024). Plaque psoriasis is the most common presentation of psoriasis. "We further found that GSDMD was prominently expressed in neutrophils, especially in Munro’s microabscesses, which were indicated by CD66b in the patients’ skin of both psoriasis vulgaris and pustular psoriasis." (PMID 39717896, 2024).
pulmonary tuberculosis (1 paper, 2023). A bacterial infection that affects the lungs and is caused by Mycobacterium tuberculosis. "In this study, transcriptome analysis of the peripheral blood of patients with pulmonary tuberculosis (PTB) revealed that S100A4 and GSDMD were significantly up-regulated in PTB patients’ peripheral blood." (PMID 37628889, 2023).
pustular psoriasis (1 paper, 2024). "Although we observed significantly increased GSDMD in neutrophils in pustular psoriasis, we were constrained to studying the established PV animal model due to the current absence of a mature GPP animal model." (PMID 39717896, 2024).
pyrexia (1 paper, 2022). "GasderminD (GSDMD), in the inflammasome, activates CASP1, a member of the cysteinyl aspartate protease (caspase, or CASP) gene family to induce pyrexia." (PMID 35296025, 2022).
reflux esophagitis (1 paper, 2025). "The results revealed a significant decrease in miR- 223 - 3p expression during the development of reflux esophagitis in HET- 1 A cells (P < 0.001), accompanied by significant increases in the expression levels of caspase- 1, NLRP3, and GSDMD (P < 0.05)." (PMID 40360974, 2025).
retinal (1 paper, 2023). "Thus, targeting GSDMD may be beneficial in preventing and treating neonatal brain, lung, and retinal damage in premature infants." (PMID 37679766, 2023).
retinal disease (1 paper, 2025). "Importantly, MCMV-infected eyes of MAIDS-10 mice deficient in either caspase-1, GSDMD, or IL-18 all consistently showed a pattern of retinal disease similar, if not identical, to that observed in the present study for MAIDS-10 mice deficient in the NLRP3, NLRP1b, or AIM2 inflammasomes." (PMID 41011779, 2025).
sarcopenia (1 paper, 2024). Progressive decline in muscle mass due to aging which results in decreased functional capacity of muscles. "Our results revealed higher expression of gasdermin D in sarcopenic muscle from DP, further suggesting a connection between impaired autophagy and NLRP3-dependent inflammation in the development of severe sarcopenia." (PMID 38338718, 2024).
scleroderma (1 paper, 2022). Scleroderma is a rare autoimmune connective tissue disorder characterized by abnormal hardening of the skin and, sometimes, other organs. "Here, we found that GSDMD was significantly up-regulated and activated in the skin of scleroderma patients and bleomycin-induced mouse model." (PMID 35396386, 2022). "Our study carefully explored the important role of pyroptosis executor GSDMD in scleroderma patients and BLM-induced skin fibrosis in mice for the first time." (PMID 35396386, 2022). "The results of RNA-seq also showed that the expressions of cytokines IL-1β and OSM and the key transcription factor IRF7 in scleroderma were down-regulated in GSDMD KO mice." (PMID 35396386, 2022). "In conclusion, our study provides insights into physiological role of GSDMD as a key mediator in the pathogenesis of scleroderma and suggests GSDMD and its related molecules as potential therapeutic targets." (PMID 35396386, 2022). "This study is the first to study the role of GSDMD in the pathogenesis of skin fibrosis in scleroderma." (PMID 35396386, 2022). "ELISA test of the tissue supernatant found that the level of IL-1β in the skin of the BLM treated group was increased, which further proved the existence of GSDMD-related pyroptosis in scleroderma mice." (PMID 35396386, 2022). "Collectively, these findings provide the first demonstration that GSDMD related pyroptosis plays an important role in scleroderma pathogenesis." (PMID 35396386, 2022). "In this study, we first demonstrated that the levels of GSDMD were up-regulated and cleaved GSDMD was present in the skin of scleroderma patients." (PMID 35396386, 2022). "Interestingly, we found that the expression of GSDMD, caspase-1, IL-1β, and IL-18 increased significantly at the early stage (days 7 and 14) of the disease in scleroderma mice." (PMID 35396386, 2022). "This was similar to the findings of immunohistochemistry of cleaved GSDMD in scleroderma patients, suggesting GSDMD may mainly play a role at the initiation and early inflammatory stage of the disease." (PMID 35396386, 2022). "Interestingly, we observed that cleaved GSDMD-positive cells were mainly scattered near the perivascular area of scleroderma skin lesions, some of them were macrophages, which proved that GSDMD induced pyroptosis occurs in scleroderma patients." (PMID 35396386, 2022). "Moreover, the protein levels of cleaved-GSDMD, cleaved caspase-1 and mature IL-1β were also elevated in scleroderma mice." (PMID 35396386, 2022). "Therefore, we further examined whether there was a GSDMD-related pyroptosis in macrophages in scleroderma." (PMID 35396386, 2022). "We cultured CD4+ T cells with the supernatant of pyroptotic BMDMs in vitro, and the resulting T cells had a stronger ability to secrete IL-17A, indicating that GSDMD-related pyroptosis in macrophages could promote T cells differentiate into Th17, which may contribute to skin fibrosis in scleroderma." (PMID 35396386, 2022). "To determine whether pyroptosis executor GSDMD plays a role in the development of scleroderma, we compared gene expression between healthy skin (n = 15) and SSc skin samples (n = 18) using microarray data in the Gene Expression Omnibus (GEO) database (GSE95065)." (PMID 35396386, 2022). "Here, we provide the first insight into the physiological function of GSDMD in skin fibrosis of scleroderma and try to describe the regulatory mechanism of GSDMD-mediated pyroptosis in the development of immunological dysfunction in scleroderma patients and mouse model." (PMID 35396386, 2022). "The result of immunofluorescence colocalization showed the presence of activated GSDMD in CD68-positive macrophages, suggesting that the pyroptosis of macrophages existed in scleroderma." (PMID 35396386, 2022).
scleroderma (continued). "In order to detect whether GSDMD induced pyroptosis occurs in scleroderma, we used immunohistochemistry staining to test the existence of the cleaved GSDMD in scleroderma skin with the excellent GSDMD antibody that recognize endogenous levels of GSDMD only when GSDMD is cleaved at Asp275." (PMID 35396386, 2022). "In order to further verify the role of GSDMD-induced pyroptosis in mice with scleroderma, we used BLM to establish scleroderma mouse model for study." (PMID 35396386, 2022). "Next, we found that GSDMD is also up-regulated and activated in BLM-induced scleroderma mice model." (PMID 35396386, 2022). "From our results of RNA-seq and RT-qPCR, Western Blot and ELISA, we can make reasonable assumptions that BLM activates GSDMD and promotes the upregulation and secretion of IL-1β, while genetic ablation of GSDMD reduces the expression of IL-1β in BLM-induced scleroderma mice." (PMID 35396386, 2022). "However, the physiological role and mechanism of GSDMD in the pathogenesis of BLM-induced skin fibrosis in mice and whether pyroptosis occurs in scleroderma patients are still unclear." (PMID 35396386, 2022). "Nevertheless, the role of pyroptosis executor gasdermin D(GSDMD), which is a downstream molecule of NLRP3 and is required for IL-1β release in some situations, has not yet been well elucidated in scleroderma." (PMID 35396386, 2022).
skin infection (1 paper, 2021). An inflammatory process affecting the skin, caused by bacteria, viruses, parasites, or fungi. "Together, these results showed that GSDMD deficiency resulted in exaggerated recruitment of inflammatory cells that may cause tissue damage and promote infection during S. aureus skin infection." (PMID 34011393, 2021). "Collectively, these results showed that the Cxcl1–Cxcr2 axis is responsible for the decreased host defence against S. aureus skin infection in the GSDMD−/− mice." (PMID 34011393, 2021). "More importantly, inhibiting the Cxcl1–Cxcr2 axis with a Cxcr2 inhibitor or anti-Cxcl1 blocking antibody rescued defects in host defence against S. aureus skin infection in the GSDMD−/− mice." (PMID 34011393, 2021). "Next, we evaluated whether inhibiting the Cxcl1–Cxcr2 axis in the GSDMD−/− mice could rescue impaired host defence against S. aureus skin infection." (PMID 34011393, 2021). "GSDMD promotes bacterial killing and prevents excess tissue damage during S. aureus skin infection." (PMID 34011393, 2021). "However, much less is known about the biological implication of GSDMD in host defence during S. aureus skin infection." (PMID 34011393, 2021).
Skin ulcer (1 paper, 2025). A discontinuity of the skin exhibiting complete loss of the epidermis and often portions of the dermis and even subcutaneous fat. "In GSDMD−/− mice, the severity of skin ulcers after modeling was significantly diminished." (PMID 40034857, 2025).
testicular degeneration (1 paper, 2024). "The size of the testis and testis–body weight ratio were larger in Gsdmdfl/flCx3cr1-cre mice than in Cx3cr1-cre mice, indicative of improved testicular degeneration in GSDMD-deficient mice." (PMID 38177538, 2024).
Thrombocytopenia (1 paper, 2023). A reduction in the number of circulating thrombocytes. "NLPR3 inflammasome components and GSDMD may be feasible targets for treating dengue‐associated thrombocytopenia and platelet defects." (PMID 36852778, 2023).
thymoma (1 paper, 2025). A neoplasm arising from the epithelial cells of the thymus. "Notably, thymomas frequently harbor mutations in epigenetic regulators, which may epigenetically silence GSDMD while promoting immune tolerance through thymic epithelial cell dysfunction." (PMID 40491921, 2025).
type 1 diabetes mellitus (1 paper, 2024). A chronic condition characterized by minimal or absent production of insulin by the pancreas. "This study demonstrated that TBK1 and GSDMD are upregulated in the SDH of type 1 diabetes mellitus (T1DM) and T2DM-related PDN mouse models." (PMID 39030571, 2024).
viral hepatitis (1 paper, 2024). An acute or chronic inflammation of the liver parenchyma caused by viruses. "The inflammasomes affect the pathological process of viral hepatitis through its downstream secretion of inflammatory cytokines interleukin-1β (IL-1β) and IL-18 or induction of pyroptosis resulting from cleaved gasdermin D (GSDMD)." (PMID 38817443, 2024).
viral pneumonia (1 paper, 2025). Inflammation of the lung parenchyma that is caused by a viral infection. "Our transcriptomic analysis suggested that the GSDMD pathway is a likely pathway through which STING regulates NETs in viral pneumonia." (PMID 40666504, 2025). "Moreover, our study revealed that STING-mediated activation of GSDMD induced NETs formation in viral pneumonia, exacerbating this condition." (PMID 40666504, 2025). "The study also revealed that blocking STING could inhibit the activation of GSDMD to inhibit NETs formation, slowing the progression of viral pneumonia." (PMID 40666504, 2025). "Therefore, GSDMD-mediated NETs formation in PR8-induced viral pneumonia is dependent on STING." (PMID 40666504, 2025). "Combined with our findings, these observations indicate that the pore-forming effect of GSDMD on neutrophil membranes depends on STING signaling, which leads to NETs formation and exacerbates the progression of viral pneumonia." (PMID 40666504, 2025). "To investigate the mechanism of action of STING and GSDMD in NETs formation in PR8-induced viral pneumonia, we examined the effects of STING and GSDMD on neutrophils." (PMID 40666504, 2025). "Strong correlations among STING, GSDMD, and NETs-related proteins were found in the lung tissues of mice with PR8-induced viral pneumonia." (PMID 40666504, 2025). "In conclusion, targeting STING is a viable therapeutic approach for viral pneumonia, and inhibiting STING also reduces GSDMD activation, thereby decreasing NETs formation and slowing the progression of viral pneumonia." (PMID 40666504, 2025). "In addition, in viral pneumonia, the expression of STING and GSDMD on neutrophils is increased." (PMID 40666504, 2025).
vitiligo (1 paper, 2022). Generalized well circumscribed patches of leukoderma that are generally distributed over symmetric body locations and is due to autoimmune destruction of melanocytes. "Further analysis of melanocytes revealed strong pyroptosis responses existed in patients with vitiligo.Results demonstrated that CASP1, CASP4, CASP6, CASP8, and GSDMD expression was significantly upregulated in melanocytes of patients with vitiligo." (PMID 35962439, 2022).
X-linked chronic granulomatous disease (1 paper, 2023). "Noteworthy, the authors also found that neutrophils from patients with X-linked chronic granulomatous disease (CGD) incapable to produce ROS from NADPH oxidase were also unable to cleave GSDMD upon stimulation with PMA." (PMID 38127952, 2023).
tumor (300 papers, 2019 to 2026). "Our objective was to evaluate the utility of GSDMD as a diagnostic and prognostic biomarker and to investigate its association with tumor burden and hematological parameters." (PMID 41977007, 2026). "Background/Objectives: Gasdermin D (GSDMD) is a critical mediator of pyroptosis-an inflammatory form of programmed cell death increasingly implicated in tumor biology." (PMID 41977007, 2026). "CAR T cell-induced pyroptosis further illustrates this complexity: granzyme B activates caspase-3 and GSDME in tumor cells, which triggers caspase-1-dependent GSDMD in macrophages, causing cytokine release syndrome." (PMID 41291696, 2025). "Collectively, these findings indicate that GSDMD exhibits cancer-type-specific expression patterns and is intricately linked to patient prognosis, suggesting a potential role in tumor development and progression." (PMID 40491921, 2025). "Gasdermin D. expression in OS has been implicated in immunogenic cell death and modulation of the tumor immune microenvironment." (PMID 41154810, 2025). "In tumor diseases, the expression of GSDMD in tumor tissues is closely associated with the tumor microenvironment and primarily regulated by tumor cells and immune cells." (PMID 39994107, 2025). "We conducted a pan-cancer analysis of GSDMD expression across TCGA datasets and investigated its association with tumor mutational burden (TMB), microsatellite instability (MSI), and mismatch repair (MMR) status." (PMID 40491921, 2025). "Gasdermin D (GSDMD), a key executor of pyroptosis, has been implicated in modulating the tumor immune microenvironment." (PMID 40491921, 2025). "In this study, we also observed a significant reduction in tumor-infiltrating Tregs (CD4+Foxp3+ T cells) in GSDMD-deficient or DSF-treated mice, presumably due to IL-2 reduction (data not shown)." (PMID 40759573, 2025). "Under pathological conditions, GSDMD expression undergoes notable changes compared to the resting state, though the patterns of alteration are inconsistent between non-tumor and tumor-associated diseases." (PMID 39994107, 2025). "High GSDMD expression is associated with aggressive tumor features, including larger tumor size and advanced TNM stage." (PMID 40868135, 2025). "To further explore the immunological relevance of GSDMD in cancer, we investigated its association with three key biomarkers of immunotherapy response: tumor mutational burden (TMB), microsatellite instability (MSI), and mismatch repair (MMR) gene expression." (PMID 40491921, 2025). "Emerging molecular markers, such as gene expression–based immune risk signatures, circulating tumor DNA, and gasdermin D overexpression, are evaluated for their prognostic and therapeutic relevance." (PMID 41154810, 2025). "Given the widespread occurrence of pyroptosis across various cancers, a pan-cancer approach is crucial for understanding the variations in GSDMD expression, distribution, and mutations across different tumor types and organs." (PMID 40491921, 2025). "GSDMD plays a pivotal role in immune responses and is closely linked to immune cell activity within the tumor microenvironment, positioning it as a promising target for improving cancer therapy." (PMID 40491921, 2025). "Increased GSDMD expression has been associated with aggressive tumor characteristics, including larger tumor size and more advanced tumor‐node‐metastasis (TNM) stages." (PMID 40783818, 2025). "Gasdermin D. (GSDMD) is a new promising biomarker: overexpression in the tumor is linked with aggressive clinical behavior and poor pathological features, and its expression has been recently identified as an independent survival prognosis factor." (PMID 41154810, 2025). "ESCRT complex responds to Ca2+ influx caused by GSDMD pore formation in inflammasome-activated cells and removes such pores to prevent pyroptosis, thus potentially implicating itself in promoting tumor progression or resistance." (PMID 38898209, 2024).